RNF17 (ring finger protein 17)
Description:
Seems to be involved in regulation of transcriptional activity of MYC. In vitro, inhibits DNA-binding activity of Mad-MAX heterodimers. Can recruit Mad transcriptional repressors (MXD1, MXD3, MXD4 and MXI1) to the cytoplasm. May be involved in spermiogenesis (By similarity).
Synonyms: TDRD4; Mmip-2; SPATA23; FLJ11045
Tractability: PROTAC: ubiquitination databases record sites on it.
Gene: Protein-coding gene on chromosome 13 (24,764,169 to 24,879,921, forward strand). Ensembl gene ENSG00000132972.
Subcellular location: Cytoplasm; Nucleus
Gene Ontology:
Molecular function: identical protein binding
Cellular component: cytoplasm; nucleus
Genetic constraint (gnomAD): Loss-of-function variants: 9 observed, 68.93 expected, observed/expected ratio (o/e) 0.13, 90% interval 0.078 to 0.23. The upper end of that interval is the gene's LOEUF score, 0.23, which puts it in group 1 of 6, group 1 being the genes least tolerant of losing a copy. Missense variants: 738 observed, 879.62 expected, observed/expected ratio (o/e) 0.84, 90% interval 0.79 to 0.89. Synonymous variants: 286 observed, 298.75 expected, observed/expected ratio (o/e) 0.96, 90% interval 0.87 to 1.06.
Homologues: Orthologues: chimpanzee RNF17 (99% identical), macaque RNF17 (96% identical), dog RNF17 (82% identical), rabbit RNF17 (80% identical), pig RNF17 (76% identical), mouse Rnf17 (75% identical), rat Rnf17 (75% identical), tropical clawed frog rnf17 (36% identical), zebrafish rnf17 (30% identical), Caenorhabditis elegans Y39B6A.25 (7% identical).
Diseases named in the same sentence as RNF17 in open-access papers:
RNF17 is named in the same sentence as 7 diseases in open-access papers, as found by Europe PMC text mining. Sharing a sentence is not in itself a finding about the gene and the disease. The quoted sentences say what the papers report.
infertile (3 papers, 2008 to 2025). "RNF17 is a key component of male germ cell differentiation, and its absence leads to infertility in male mice, with germ cells ceasing development at the round spermatid stage and failing to produce sperm." (PMID 40460050, 2025). "RNF17 localizes to a new form of nuage, RNF17-granules; RNF17 knockouts lack these granules and the male mice are infertile as well." (PMID 18507824, 2008).
male infertility (2 papers, 2020 to 2023). The inability of the male to effect fertilization of an ovum after a specified period of unprotected intercourse. "Rnf17 mutant males have been shown to exhibit severe post-meiotic germ cell loss culminating in total male infertility and previously published analyses of Adad2 mutant testis histology suggest a similar profile of germ cell loss during round spermatid development." (PMID 37428816, 2023).
Azoospermia (1 paper, 2019). Absence of any measurable level of sperm,whereby spermatozoa cannot be observed even after centrifugation of the semen pellet. "Interestingly, we identified meiotic proteins a priori unrelated to the UPS such as DAZL (deleted in azoospermia), SPAG1 (Sperm-associated antigen 1), SPATA5/20 (Spermatogenesis-associated protein 5/20), the tudor domain proteins TDRD1/6/9, MAEL (repressor of transposable elements), and RNF17." (PMID 31437213, 2019).
liver cancer (1 paper, 2015). An epithelial or non-epithelial malignant neoplasm that arises from the liver. "For the UC Bead GRN, RNF17 (TDRD4) is a potential liver cancer CT antigen and TMED7 was observed to be upregulated in a nasopharyngeal carcinoma cell line and described to act as a major immune system switch." (PMID 25971253, 2015).
tumor (2 papers, 2015 to 2020). "Furthermore, the identified hub genes of the individual GRNs, e.g., HID1/DMC1 (tumor development), RNF17/TDRD4 (cancer antigen) and CYP4A11 (angiogenesis/ metastasis) are known cancer associated markers." (PMID 25971253, 2015).
cancer (1 paper, 2015). A tumor composed of atypical neoplastic, often pleomorphic cells that invade other tissues. "We identified hub genes such as HID1 (RNAseq) RNF17 (TDRD4) (Bead), CYP4A11 (Oligo) for the individual GRNs which show in the literature strong evidence for cancer related diagnostic and prognostic properties." (PMID 25971253, 2015).
RNF17 also shares sentences with these, for which no sentence is quoted: nasopharyngeal carcinoma (1 paper).